FGFR3 (fibroblast growth factor receptor 3)
Diseases named in the same sentence as FGFR3 in open-access papers (continued):
Sharing a sentence is not in itself a finding about the gene and the disease.
lung adenocarcinoma (continued). "In conclusion, we demonstrated that miR-24-3p/FGFR3 axis managed the occurrence and development of lung adenocarcinoma in an EMT-related manner." (PMID 29850625, 2018). "More importantly, clinical evidences in this study also confirmed that FGFR3 overexpression predicted adverse clinical outcomes in patients with lung adenocarcinoma." (PMID 29850625, 2018). "To study potential function of FGFR3 in lung adenocarcinoma progression, we constructed H1299 FGFR3 cell by infecting with corresponding lentivirus, taking H1299 NC cell as control." (PMID 29850625, 2018). "Overexpression of FGFR3 not only significantly promoted proliferation but also obviously facilitated cell invasion and migration in lung adenocarcinoma." (PMID 29850625, 2018). "To investigate the underlying effects of FGFR3 in prognosis, we then assessed the relationship between FGFR3 protein expression and its prognosis value in lung adenocarcinoma patients." (PMID 29850625, 2018). "Briefly, among newly detected mutations in lung adenocarcinoma, AKT, BRAF, FGFR2, HRAS, and KIT mutations were detected in one sample (1.3%), MAP2K in two samples (2.6%), MET in 4 samples (5.9%), and FGFR3 in 5 samples (7.4%)." (PMID 28404952, 2017). "However, a study reported the significant up-regulation of FGFR3 in bone metastasis of lung adenocarcinoma." (PMID 39275122, 2024). "And In lung adenocarcinoma, miR-24-3p could suppress cell proliferation, migration, and invasion by regulating FGFR3 directly." (PMID 33123467, 2020). "Besides, FGFR3 was directly targeted by miR-24-3p and upregulation of FGFR3 was related to worse prognosis in patients with lung adenocarcinoma." (PMID 29850625, 2018). "Owing to the direct regulation towards FGFR3, miR-24-3p could interfere with the potential of proliferation, migration, and invasion in lung adenocarcinoma, following variations of EMT-related protein expression." (PMID 29850625, 2018). "Nevertheless, the exact roles of miRNA in regulating FGFR3 in lung adenocarcinoma and whether this regulation is involved in tumor progression are still in need of further investigations." (PMID 29850625, 2018). "Likewise, the Kaplan–Meier plotter database also revealed that higher levels of FGFR3 were closely related to worse prognosis in lung adenocarcinoma individuals." (PMID 29850625, 2018). "However, the active effects and molecular mechanism of FGFR3 in lung adenocarcinoma are only partially understood and warrant further investigation." (PMID 29850625, 2018). "Furthermore, downregulation of miR-24-3p was partially generated by the upregulation of FGFR3 in lung adenocarcinoma." (PMID 29850625, 2018). "Collectively, our findings above indicated that FGFR3 may be a novel prognostic biomarker for the diagnosis and management of lung adenocarcinoma." (PMID 29850625, 2018). "Furthermore, our results suggested that FGFR3 overexpression was related to the worse outcome of individuals with lung adenocarcinoma." (PMID 29850625, 2018). "In addition, miR-24-3p can inhibit lung adenocarcinoma progression by mediating FGFR3 signaling." (PMID 34511042, 2021). "Moreover, miR-24-3p can interfere with lung adenocarcinoma progression through FGFR3 signaling." (PMID 34511042, 2021). "Taken together, these findings define a novel insight into the miR-24-3p/FGFR3 signaling axis in regulating lung adenocarcinoma progression and suggest that targeting the miR-24-3p/FGFR3 axis could be an effective and efficient way to prevent tumor progression." (PMID 29850625, 2018). "Due to the inhibitory roles of FGFR3 in invasion and migration of cancer cells, we then investigated whether miR-24-3p, the upstream molecule of FGFR3, affected migration and invasion of lung adenocarcinoma cells." (PMID 29850625, 2018).
lung adenocarcinoma (continued). "In light of the inhibitory effect of miR-24-3p in impairing processes of proliferation, migration, and invasion in lung adenocarcinoma and the direct interaction between miR-24-3p and FGFR3, we next explored whether FGFR3 took effects in miR-24-3p-mediated lung adenocarcinoma progression." (PMID 29850625, 2018). "However, whether the miR-24-3p/FGFR3 signaling is involved in EMT in lung adenocarcinoma remains uncertain." (PMID 29850625, 2018). "Moreover, FGFR3 overexpression could reverse the effect of miR-24-3p on these EMT markers in lung adenocarcinoma cells." (PMID 29850625, 2018). "We present the first portrait of clinically actionable alterations in lung adenocarcinoma of Indian origin that includes EGFR, KRAS, EML4-ALK, AKT1, PIK3CA, FGFR4 and ERBB2, similar to that identified in other ethnic groups, and an additional subset of patients with FGFR3 mutations." (PMID 27998968, 2017). "Five genes were flagged as mutant in all 8 lung adenocarcinoma samples namely RET, APC, FGFR3, NPM1 and PDGFRA when the least stringent QBVD threshold was applied (QBVDi = 71)." (PMID 23922754, 2013). "The FGFR3 mRNA level is also a negative prognostic factor for lung adenocarcinoma and squamous cell laryngeal cancer, where high FGFR3 expression was significantly correlated with shorter overall survival (OS)." (PMID 36142417, 2022). "To further confirm this result, we performed IHC to score the FGFR3 expression in a second cohort of paired lung adenocarcinoma and noncancerous tissues (n = 78)." (PMID 29850625, 2018). "We measured FGFR3 expression in the initial cohort of 22 paired human lung adenocarcinoma and noncancerous tissues by Western blot." (PMID 29850625, 2018).
acanthosis nigricans (21 papers, 2012 to 2025). A melanotic cutaneous lesion that develops in the axilla and other body folds. "For example, mutations in FGFR3 lead to familial acanthosis nigricans, which results in skin pigmentation abnormalities." (PMID 38728357, 2024). "It is known that acanthosis nigricans is associated with other FGFR3‐related skeletal dysplasias; however, dermopathy is prevalent and severe in TD." (PMID 34597445, 2021). "The role of FGFR3 in intramembranous ossification is highlighted by the identification of FGFR3 mutations in craniosynostosis disorders like Crouzon syndrome with acanthosis nigricans and Muenke syndrome." (PMID 33919228, 2021). "He concluded that FGFR3 mutation analysis should be considered in case of the coexistence of acanthosis nigricans and a skeletal dysplasia and advised testing for hyperinsulinemia, especially if FGFR3 gene mutation is confirmed." (PMID 25505998, 2014). "Crouzon syndrome with Acanthosis Nigricans has been linked to the A391E mutation in the transmembrane (TM) domain of Fibroblast growth factor receptor 3 (FGFR3)." (PMID 23437153, 2013). "The A391E mutation in fibroblast growth factor receptor 3 (FGFR3) is the genetic cause for Crouzon syndrome with Acanthosis Nigricans." (PMID 23437153, 2013). "FGFR3 is a gene known to be associated with acanthosis nigricans, and previous research has suggested that it might also be implicated in the progression of PCOS." (PMID 39407944, 2024). "Mutation in the FGFR3 gene may also cause Crouzon syndrome with acanthosis nigricans, Muenke syndrome, familial acanthosis nigricans and CATSHL (camptodactyly, tall stature, scoliosis and hearing loss) syndrome." (PMID 34070375, 2021). "We report a patient with a clinical presentation that overlaps with Pfeiffer syndrome type 3 with a de novo FGFR3 NM_000142.4:c.1428C>A change resulting in a missense p.Ala391Glu variant associated with Crouzon syndrome with acanthosis nigricans (CAN) (OMIM 612247)." (PMID 31016899, 2019). "Thus, it can be expected that the pathology in Crouzon syndrome with Acanthosis Nigricans is directly linked to the elevated activation of mutant FGFR3." (PMID 23437153, 2013). "Acanthosis nigricans appears to arise as a direct result of constitutive activation of FGFR3." (PMID 30606190, 2019). "Consequently, further exploration of the genetic foundations, with a particular emphasis on FGFR3 and its interaction with hormonal and inflammatory factors, could shed light on why some adolescents with MASLD and PCOS are more prone to developing acanthosis nigricans." (PMID 39407944, 2024).
gastric cancer (21 papers, 2014 to 2025). A primary or metastatic malignant neoplasm involving the stomach. "The Cancer Genome Atlas (TCGA) dataset manifests 432 cases of gastric cancer (SC) harboring FGFR3 amplification wherein 24 cases showed copy number gain and 12 cases with copy number loss." (PMID 34765202, 2021). "A recent study identified the FGFR3/AKT axis as an escape pathway responsible for trastuzumab resistance in gastric cancer, thus indicating the inhibition of FGFR3 as a potential strategy to modulate this resistance." (PMID 34765202, 2021). "Here, we report a case of gastric cancer that responded favorably to FGFR3 targeting with Pazopanib in combination with chemotherapy agents based on multi‐analyte the tumor profiling." (PMID 34765202, 2021). "Further studies may be necessary to establish the viability of such combination regimens in FGFR3 amplified gastric cancer patients." (PMID 34765202, 2021). "Besides, FGFR3 overexpression was found in gastric cancer and liver cancer." (PMID 33381388, 2020). "However, miR-192 serves as a poor prognosis marker in other cancer types including neuroblastoma targeting Dicer1, gastric cancer targeting RAB11-FIP2 and SMG-1, NSCLC targeting the FGFR3/RB1 pathway, hepatocellular carcinoma targeting SEMA3A, and pancreatic cancer targeting SIP1." (PMID 33614788, 2021).
Muenke syndrome (20 papers, 2006 to 2025). "Specific missense substitutions in this linker region in FGFR1, FGFR2, and FGFR3 cause Pfeiffer, Apert, and Muenke syndromes, respectively." (PMID 40259859, 2025). "Hypochondroplasia and Muenke syndrome due to FGFR3 mutations are connected with bilateral dysgenesis of the medial and temporal lobes." (PMID 39735065, 2024). "Premature fusion of cranial sutures is most often associated with Apert syndrome (FGFR2), Muenke syndrome (FGFR3), Crouzon syndrome (FGFR2), Pfeiffer syndrome (FGFR2, FGFR1), and Saethre-Chotzen syndrome (TWIST1)." (PMID 37629737, 2023). "A similar species-dependent discrepancy in effects of mutant receptor signaling has been observed in Fgfr3P244R-mutant mice that express the FGFR3-mutation associated with coronal synostosis in human Muenke syndrome." (PMID 32566365, 2020). "Syndromes associated with cleft palate include those arising from mutations in FGFR1-3; e.g. Apert syndrome (FGFR2), Muenke syndrome (FGFR3), Crouzon syndrome (FGFR2, FGFR3) and Hartsfield syndrome (FGFR1)." (PMID 31613912, 2019). "There is precedence of notable phenotypic variability reported for the p.Pro250Ala variant in FGFR3 which can manifest as Muenke syndrome or nonsyndromic CS." (PMID 31016899, 2019). "Craniosynostosis is the primary phenotypic consequence of certain FGFR3 mutations, particularly in Muenke syndrome." (PMID 30606190, 2019). "Individuals with Muenke syndrome due to mutations in FGFR3 gene presented left hemimegalencephaly." (PMID 39735065, 2024). "Furthermore, mice with FGFR3 P244R mutation (equivalent to the human P250R mutation), a genetic model for Muenke syndrome, show a rounded skull and shortened snout with dental malocclusion which are similar to Muenke syndrome features in humans." (PMID 37325554, 2023). "For example, the P250R mutation in FGFR3, causing Muenke syndrome, increases ligand binding." (PMID 23437153, 2013). "Phenotypic overlap occurs with Muenke syndrome, which is caused by a specific FGFR3 mutation." (PMID 16740155, 2006). "Nevertheless, FGFR3P244R/+ mutant mice, a model of Muenke syndrome with FGFR3 gain-of-function, displayed mild skull deformities and rarely showed premature fusion of the coronal suture." (PMID 37325554, 2023). "In the FGFR3 mouse model for Muenke syndrome (FGFR3P244R/+), Deiters' cells transform into pillar cells and these two types of supporting cells can reversibly switch fates in an FGF-dependent manner." (PMID 26092122, 2015). "We have now determined the sequence of FGFR3 cDNA in the rabbit and determined that no structural mutations are present to explain the craniosynostotic phenotype, such as the P250R mutation commonly observed in Muenke syndrome." (PMID 23738319, 2013).
prostate carcinoma (19 papers, 2005 to 2025). A carcinoma that arises from epithelial cells of the prostate gland. "Recently, a novel FGFR3 splice variant was reported in African American prostate cancer (FGFR3-S) that was associated with a poor prognosis and increased cell proliferation and motility." (PMID 34830836, 2021). "FGFR3 binds to multiple FGFs known to be upregulated in human prostate cancer (FGF1, FGF2 and FGF8), and is potentially important in prostate cancer." (PMID 15655558, 2005). "Immunoreactivity for FGFR3 was observed in majority (>95%) of the cases examined, both specimens from prostate carcinoma and BPH." (PMID 15655558, 2005). "Notably, the most common non–FDA-approved indications were cancers with limited targeted therapies available: pancreatic cancer for FGFR2 fusions (prevalence of 0.5%) and prostate cancer for FGFR3 and NRG1 fusions (combined prevalence of 0.4%)." (PMID 41091579, 2025). "Hence, we conclude that there is no significant change in the overall expression and localisation of the FGFR3 in human prostate cancer." (PMID 15655558, 2005). "Future directions for this work include further characterization of EYA1, CSMD3, FGFR3, and PCDH15 in prostate cancer metastases and the roles of oxidative phosphorylation and FGFR3 in prostate cancer health disparities." (PMID 38067373, 2023). "First, we examined for abnormal expression of FGFR3 and FGFR4 in clinical prostate cancer specimens." (PMID 15655558, 2005). "We showed that FGFR3 is expressed in the majority of BPH and prostate cancer." (PMID 15655558, 2005). "On the other hand, some studies have shown that FGFR-3 is not overexpressed in benign prostatic hyperplasia as well as in prostate cancer itself corroborating our results that showed that the levels of this receptor decrease with the advancement of this malignant disease." (PMID 28499383, 2017). "Overall, 13.6% and 8.2% of FGFR2 fusions were in nonapproved breast and pancreatic cancer indications, respectively, 22.2% of FGFR3 fusions were in nonapproved NSCLC, and 19.4% and 10.2% of NRG1 fusions were in nonapproved breast and prostate cancers, respectively." (PMID 41091579, 2025). "However, we did not observe any significant change in the levels of FGFR3 expression between BPH and prostate cancer." (PMID 15655558, 2005).
squamous cell carcinoma (17 papers, 2005 to 2025). A carcinoma arising from squamous epithelial cells. "SNapShot®-analysis showed FGFR3 mutations in 6 of 71 samples (8.5%, all p.S249C, n = 3 pure squamous carcinomas and n = 3 mixed carcinomas)." (PMID 27669755, 2016). "In our study 6 of 71 (8.5%) tumor samples (n = 3 pure squamous carcinomas and n = 3 mixed carcinomas) contained an FGFR3 p.S249C mutation, all of them being grade 2 or higher and stage 3 or higher." (PMID 27669755, 2016). "As all tumors with FGFR3 mutations were of the squamous type, we only used gene expression profiles from squamous cell carcinomas to compare tumors of same histological type and to minimize gene expression differences caused by different histology." (PMID 15869706, 2005). "Also, different subtypes also had their own specific variants, such as MET in adenocarcinoma, FGFR1 and FGFR3 in squamous cell carcinoma and MYC in small cell lung cancer." (PMID 31616594, 2019). "In this study, TMB-high status was more common in squamous cell carcinoma, as well as in tumors harboring mutations in NOTCH1, FGFR3, or FGFR4." (PMID 34860358, 2022). "Targeting of FGFR1 was found to increase radiation-induced killing of mesothelioma cells, whereas inhibition of FGFR3 enhanced radiosensitivity of squamous cell carcinomas." (PMID 31948066, 2020). "FGFR2, FGFR3, and FGFR4 expression were elevated in squamous cell carcinoma, and a high expression of FGFR1, FGFR2, FGFR3, and FGFR4 were associated with a less aggressive phenotype." (PMID 27154171, 2016). "The FGFR3::TACC3 fusion has been reported in subsets of diverse cancers including urothelial and squamous cell carcinomas (SCC)." (PMID 39387893, 2025). "FGFR3, LYPD3, PVRL4, SDC1, and TACSTD2 exhibited significantly elevated expression levels in squamous cell carcinoma relative to adenocarcinoma." (PMID 40046734, 2025). "Of note, squamous cell carcinoma cases had enrichment of fusions involving FGFR1 (0.9% vs 0.3%), FGFR3 (0.8% vs 0.2%), and PIK3CA (0.5% vs <0.01%)." (PMID 39664186, 2024). "FGFR1 was more highly expressed in adeno-/adenosquamous carcinoma, while FGFR2, FGFR3, and FGFR4 expression was more prominent in squamous cell carcinoma (P = 0.020, P < 0.001, P < 0.001, and P = 0.020, respectively)." (PMID 27154171, 2016). "FGFR1 was highly expressed in adeno-/adenosquamous carcinoma (P = 0.020), while FGFR2, FGFR3, and FGFR4 expression were more prominent in squamous cell carcinoma (P < 0.001, P < 0.001, and P = 0.020, respectively)." (PMID 27154171, 2016). "In a large German study analyzing RNA-based NGS data from 3309 NSCLC patients, 21 FGFR3::TACC3-positive cases (0.63%) were identified, predominantly among male patients with a median age of 69 years, a higher prevalence of squamous cell carcinoma, and favorable responses to immunotherapy." (PMID 41301039, 2025). "The fusion of the fibroblast growth factor receptor 3 (FGFR3) to the transforming acidic coiled-coil 3 (TACC3) was observed independent of the tumor type (five squamous cell carcinomas and two adenocarcinomas)." (PMID 38256374, 2024). "However, FGFR3 alteration was rarely observed in NSCLC, and was detected in 0.1% of adenocarcinomas and 0.6% of squamous cell carcinomas, respectively." (PMID 35377040, 2023). "Alterations in ALK and FGFR3, present in the RTK/RAS/MAPK signaling pathway, have been reported in cutaneous squamous cell carcinomas; in particular, alterations in ALK have been described as drivers of metastases in squamous cell carcinomas to the lymph nodes." (PMID 39273494, 2024). "While FGFR1 amplifications have been found in up to 22% of squamous cell carcinomas of the lung and about 15% in head and neck cancers, we found neither FGFR1, FGFR2, nor FGFR3 amplifications by FISH in squamous differentiated bladder cancer." (PMID 27669755, 2016).